TLR8 (toll like receptor 8)
Diseases named in the same sentence as TLR8 in open-access papers (continued):
Sharing a sentence is not in itself a finding about the gene and the disease.
cancer (continued). "As effective agents to treat cancer and infectious diseases and to improve immune responses, agonists of TLR7 and TLR8 have attracted great attention." (PMID 33537035, 2020). "Through structure-based drug design, we discovered a novel, highly potent and selective small molecule TLR8 agonist with little activity on TLR7, namely DN052 for cancer indications." (PMID 35006413, 2020). "The TLR8 agonist motolimod (VTX-2337) has been evaluated in clinical trials, is well tolerated and shows promise activating the immune system in cancer patients." (PMID 33008037, 2020). "As a consequence of exosomic miR-21 and miR-29a binding to TLR8, TAMs secrete increased IL-6 and TNF-α, creating a sterile inflammatory TME that promotes cancer growth and dissemination." (PMID 27231010, 2016). "Both miR-21 and miR29a can act within cancer cells or can be delivered from cancer cells to macrophages by microvesicles and can subsequently bind intracellular TLR7 or TLR8." (PMID 25743773, 2015). "Stimulation with the TLR7/TLR8 ligand R848 induced a relative increase in proliferation in TLR7+ and TLR8+ in PANC1 cancer cells compared to empty vector treated PANC1 cells (TLR7+, 206% and TLR8, 251% vs. empty vector, 170%; P<0.02 and P<0.0001)." (PMID 26134824, 2015). "Cell morphology of cancer cells and positive staining for CD34 indicated that cells expressing TLR7 and TLR8 were indeed cancer cells." (PMID 26134824, 2015). "Our group found that mMDSCs isolated from the peripheral blood of normal volunteers and cancer patients differentiated into M1-like macrophages when exposed to several TLR7 and TLR8 agonists." (PMID 26343193, 2015). "Stimulation of TLR7/TLR8 overexpressing PANC1 cells resulted in elevated NF-κB and COX-2 expression, increased cancer cell proliferation and reduced chemosensitivity." (PMID 26134824, 2015). "Potentially, not all cancers cause pDC hypofunction or cause it to various degrees, which would explain observations that some pDCs responded to signaling through TLR7/TLR8." (PMID 36768258, 2023). "To test how cells cultured with or without anti-cancer drugs respond to activation stimuli, we stimulated cells with the TLR8 agonist CL-075, which is both effective at activating macrophages and DCs in serum-free media as well." (PMID 36451019, 2023). "The intracellular TLRs (TLR3, TLR7, TLR8, and TLR9 in human) can detect viral and bacterial nucleic acids, playing an important role in host immune response and potentially in the treatment of cancer." (PMID 36476317, 2022). "The cell context-dependent adjuvant activity of TLR8 and TLR7/8 RNA ligands described here might be important for the future optimization of γδ T-cell based cancer immunotherapy." (PMID 34315922, 2021). "Furthermore, we analyzed TLR7 and TLR8 in dissociated cells derived from the same patient tissues together with CD34, a marker for endothelial cells and known to be expressed by cancer cells with neoangiogenetic potential, by FACS and immunohistochemical analysis (cytospins)." (PMID 26134824, 2015). "We identified Toll-like receptor 1 (TLR1), TLR2, TLR4 and TLR8 gene expression levels and downstream gene, i.e., interleukin-6 (IL-6), IL-8, interferon-α (IFN-α) and myeloid differentiation primary-response protein-88 (MyD88), expression levels in CRC patients and in cancer cell lines." (PMID 25547486, 2014). "Likewise, other TLR receptors were also decreased, with the exception of TLR8, in the carcinoma epithelium, but statistical significance was not reached, possibly due to individual differences in expression levels in ex vivo samples." (PMID 22013487, 2012).
bacterial infections (10 papers, 2014 to 2025). "Altogether, these results indicate that TIRAP can influence IRF5-mediated TLR8 signaling also during bacterial infection, which is especially clear for the induction of IL-12A expression by GBS." (PMID 35884781, 2022). "While the impact of TLR8 in bacterial infections in vivo still is unclear, we find these new data interesting in the context of human MyD88- and IRAK-4 deficiency, where signaling by most TLRs and IL-1Rs is lost." (PMID 31214180, 2019). "More recently, TLR8 has been reported to be a general sensor of RNA breakdown products and shown to be important also for the recognition of bacterial infections." (PMID 29896111, 2018). "In this study, we demonstrate that IFNα, a cytokine that modulates the early innate immune responses toward viral and bacterial infections, potently enhances the production of IL-6 in neutrophils stimulated with R848, a TLR8 agonist." (PMID 26790609, 2016). "As an endosomal ssRNA-sensing receptor, TLR8 is relevant both for viral and bacterial infections." (PMID 35884781, 2022). "LNC_001066 and LNC_000231 co-regulated the expressions of immune-related target genes, IRAK3 and TLR8, to participate in the progress of host immune response in defensing bacterial infection through apoptosis and toll-like receptor signaling pathway, respectively." (PMID 30760749, 2019).
infectious disease (7 papers, 2013 to 2024). A disorder directly resulting from the presence and activity of a microbial, viral, or parasitic agent in humans. "TLR8 polymorphisms have been described in infectious diseases with a genetic effect localized to a functional variant at exon 1 (rs3764880, Met1Val)." (PMID 23468661, 2013). "The important down-regulated genes in LBW newborns associated with these infectious diseases were TLR-8, RIG-1 and MDA-5." (PMID 23626859, 2013). "Regarding the receptor, TLR8 has been recently characterized as being involved in infectious diseases." (PMID 38980867, 2024).
inflammation (4 papers, 2017 to 2025). Aberrant reaction of the microcirculation characterized by movement of fluid and leukocytes from the blood into extravascular tissues. "TLR8, a gene encoding Toll-like receptor 8, was predominantly expressed in peripheral blood leukocytes, playing a fundamental role in antimicrobial immune responses and autoimmune inflammation." (PMID 32802866, 2020). "In this regard, TLR8 expression has been reported to be selectively activated in inflamed colonic epithelium of IBD-affected subjects and its mucosal expression directly correlates with the severity of intestinal inflammation." (PMID 29312324, 2017). "In addition, other danger signal receptors independently of STING or TLR9 may be activated leading to type I IFN/IFNAR-dependent pulmonary inflammation including MDA5/RIG-l, TLR4/MyD88, TLR7MyD88 or TLR8/MyD88,)." (PMID 31619733, 2019).
neurodegenerative disease (1 paper, 2021). A disorder of the central nervous system characterized by gradual and progressive loss of neural tissue and neurologic function. "Out of those miRNAs miR-100-5p and miR-298-5p, which have consistently been linked to neurodegenerative diseases, entered microglia, located to their endosomes, and directly bound to human TLR8." (PMID 34838071, 2021).
neurological disease (1 paper, 2025). "This underscores the importance of studying TLR7 and TLR8 in human experimental models within the context of neurological disease." (PMID 41322409, 2025).
TLR8 also shares sentences with these, for which no sentence is quoted: viral diseases (4 papers); antibody deficiency (2); B-cell chronic lymphocytic leukemia (2); candidiasis (2); Chronic Hepatitis C (2); cryptococcosis (2); genital warts (2); inflammatory bowel disease (2); Insulin resistance (2); lupus nephritis (2); metabolic disease (2); mycoses (2); Nephropathy (2); paracoccidioidomycosis (2); type 2 diabetes (2); vitiligo (2); acne (1); acute bronchiolitis (1); acute respiratory distress syndrome (1); alcohol (1); benign neoplasm (1); bladder transitional cell carcinoma (1); Bowen’s disease (1); C. perfringens infection (1); cardiac sarcoidosis (1); cardiovascular disease (1); Chagas disease (1); chronic pancreatitis (1); chronic viral hepatitis (1); coeliac disease (1).
A further 42 diseases each share a sentence with TLR8 in 1 paper.